SNORD114-14 (small nucleolar RNA, C/D box 114-14)
Synonyms: 14q(II-14)
Gene: Small nucleolar RNA gene on chromosome 14 (100,972,103 to 100,972,177, forward strand). Ensembl gene ENSG00000199593.
Gene Ontology:
Biological process: RNA processing
Cellular component: nucleolus
Homologues: Orthologues: chimpanzee SNORD114-14 (100% identical), macaque SNORD114-14 (97% identical), mouse Gm23787 (75% identical), guinea pig SNORD114-14 (68% identical), rat Snord114-4 (68% identical). Paralogues in human: SNORD114-12 (92% identical), SNORD114-3 (85% identical), SNORD114-17 (81% identical), SNORD114-21 (81% identical), SNORD114-19 (80% identical), SNORD114-25 (80% identical), SNORD114-28 (79% identical), SNORD114-9 (79% identical), SNORD114-13 (77% identical), SNORD114-15 (77% identical), SNORD114-22 (77% identical), SNORD114-23 (77% identical), and 26 more.